CD4 (CD4 molecule)
Diseases named in the same sentence as CD4 in open-access papers (continued):
Sharing a sentence is not in itself a finding about the gene and the disease.
tumor (continued). "have demonstrated that the high expression of TIM-3 is associated with head and neck squamous cell carcinoma lymph node metastasis and that the mAb targeting TIM-3 can be used to restore the function of CD4+TIM-3+ and CD8+TIM-3+ T cells to inhibit tumor growth and metastasis." (PMID 34367975, 2021). "The authors went further in dissecting the underlying mechanism by showing that controlled stimulation of dendritic cell P2X7R triggered the release of IL-18 (but curiously not of IL-1β) that in turn stimulated anti-tumor activity of NK and CD4+ lymphocytes." (PMID 33818742, 2021). "As our previous study showed that the presence of TLS-B cells in the tumor microenvironment mainly favors intratumor CD4+ T cell clonal expansion, we analyzed the expression of 550 immune-related genes in sorted TIL CD4+ T cells from 26 NSCLC patients in relation to their TLS-B cell densities." (PMID 33763071, 2021). "However, the expression levels of PTX3 in LUAD were significantly negatively correlated with tumor purity and positively correlated with B cells, CD8+ T cells, CD4+ T cells, neutrophils, and dendritic cells." (PMID 34745947, 2021). "CD4+ and CD8+ T lymphocytes are the major components of T cell-mediated anti-tumor immunity." (PMID 34639167, 2021). "Thus, CD4+ and CD8+ effector memory T cells appear to indicate both tumor response and adverse events." (PMID 34360781, 2021). "TOCA 511 resulted in the promotion of T cell expansion (Th1, Th2 in CD4+, CD8+), mediated antitumor immune response, and concentrated the effect of drugs at the tumor site which increased direct tumor cell death, alterations in immune cell infiltration, and improved survival." (PMID 33671796, 2021). "The combination of RT+CpG+OX40 resulted in favorable improvements in the ratio of effector T cells to Tregs in the TME, increased expression of proinflammatory genes in the TME, and activated CD4+ and CD8+ T cells in the tumor draining lymph node (TDLN) and spleen." (PMID 34868010, 2021). "Moreover, those patients who developed HCC after antiviral therapy had CD4 and CD8 T cells with significantly lower cytokine release and proliferative capacity compared to those patients that remained tumor-free." (PMID 34209393, 2021). "CD8+ T cells take a leading position in anti-tumor response among the tumor-infiltrated immune cells and activated effector T cells in the TME mainly depend on glycolysis and FAS, while memory T cells and CD4+ regulatory T cells maintain their functions by enhancing FAO." (PMID 34888248, 2021). "Furthermore, granzyme B secretion by CD4+ and CD8+ T cells were higher in the tumor lesions of mice treated with compound 968 with anti-PD-L1 antibody compared with the other treatment groups." (PMID 34944392, 2021). "Furthermore, iNKT cell help was provided for multiple epitope-specific CD8 and CD4 T cell responses, and a de novo antibody response was observed in NY-ESO-1 positive tumor-bearing mice via PLGA nanoparticle-mediated co-delivery." (PMID 33717196, 2021). "Furthermore, a high frequency of the CD4+ and CD8+ tumor-infiltrating lymphocytes (TILs) express PD-1." (PMID 34912335, 2021). "In a similar manner, tumor-induced human IL-10-producing B cells or plasmablasts have been described to suppress IFN-γ and GrB expression by CD8+ T cells, as well as pro-inflammatory cytokines secreted by CD4+ T cells." (PMID 33995344, 2021). "To determine whether the functions of immune cells such as T cells were impacted by the lack of the CD200-CD200R interaction, we quantified IFN-γ and TNF-α levels in CD4+ and CD8+ tumor infiltrating lymphocytes (TIL)." (PMID 34692697, 2021). "ATRA decreased the expression of immunosuppressive genes through the downregulation of TGF-β, PD-L1, IL-10, and IDO in MDSCs and upregulated MHC class I homologs MICA and MICB on tumor cells, enhancing NK cell activity and cytotoxicity of T cells in the CD8− and CD4− immune response." (PMID 34025641, 2021).
tumor (continued). "CD20+ TILs may support an increase in CD4+ and CD8+ TILs, which altered the anti-tumor response, resulting in a positive prognosis." (PMID 33726701, 2021). "The mature DCs and nonactivated lymphocytes are cultured with CD4+ T cells and 5-aza-2′-deoxycytidine, a DNA-demethylation agent, which induces the expression of tumor antigens." (PMID 33803885, 2021). "The immune cell analyses revealed a significant higher CD4 proportion in those animals without detectable tumor growth." (PMID 34070094, 2021). "In addition, donor CD4+ and CD8+ T cells from Itk–/− mice clear tumour cells but have significantly delayed development of GVHD." (PMID 34919342, 2021). "For the elimination of MHC-class II negative tumor cells, CD4+ T cells display a number of other functions." (PMID 33546283, 2021). "The isolated tumor-infiltrating DCs in mice that received AAA-CD4+ T-cell therapy showed significantly higher expression of MHC class II molecules, compared to mice in the auto-CD4+ T cell group at 4 h after therapy." (PMID 34625113, 2021). "As expected, the CD4 + /CD8 + T cell percentage was obviously increased after NRT cell infusion, suggesting an increase in the number of TILs infiltration into the tumour tissue." (PMID 34291357, 2021). "We found it particularly important that the ratio of CD8+ TNFR2+ PD-1+ TILs over either of these two subsets of CD4+ TNFR2+ TILs (CD4+ TNFR2+ FOXP3+ and CD4+ TNFR2+ PD-1+) was significantly increased in chemotherapy-treated mice and was strongly connected to reduced tumor volumes." (PMID 34201054, 2021). "The expansion of CD4+ T cells is not as predominant as that of CD8+ T cells in the tumor microenvironment." (PMID 34944847, 2021). "Next, we compared the tumor infiltration levels among PAAD with different somatic copy number alterations for each CXC chemokine and found that the somatic copy number alterations for the CXC chemokines can inhibit CD4+ T cell infiltration." (PMID 34497764, 2021). "CR intervention also significantly increased the frequencies of tumor-cytotoxic effector T cells (Eff CD8+ and CD4+) in the spleen and peripheral blood, including cytotoxic granzyme B (GrB+) expressing effector T cells in the spleen, such as GrB+CD8+ and cytotoxic GrB+CD4+." (PMID 34707136, 2021). "Notably, by immunochemistry analysis, there was a significantly lower count of CD4+ and CD8+ tumor-infiltrated lymphocytes in the VTT samples compared with their primary tumor tissues from our cohort." (PMID 34249685, 2021). "Aside from CD8+ T cells, CD4+ T cells, also known as T-helper (Th) cells, display a non-negligible role in defense against tumor as well, and the mechanisms behind them are diverse." (PMID 34831048, 2021). "Interestingly, this would point to a possible cytotoxic CD4+ activity, as in CD8+ depleted mice there was still a reduced anti-tumour response." (PMID 34276688, 2021). "One is antitumor cells mainly composed of CD4+ Th1 cells, CD8+ cytotoxic T lymphocytes (CTLs), NK cells, M1 macrophages, and dendritic cells, while the other is capable of promoting tumor growth and includes CD4+ FOXP3+ T cells (Tregs), CD4+ Th2 cells, and M2 macrophages." (PMID 34888385, 2021). "Interestingly, our results indicated that FXR can impede the generation and secretion of tumor Exos, and an FXR agonist can inhibit the increased expression of PD-L1 on N-Exos while restoring the modulation of CD4+ T cells by N-Exos." (PMID 34888230, 2021). "It appears, therefore, that both CD4+ Th1 and CD8+ cytotoxic responses against LMP1 and other tumor antigens are repressed in NPC contributing to an immunosuppressive TME that not only favors viral persistence, but also supports tumor cell growth and survival." (PMID 33718235, 2021). "The infiltration of CD4+ and CD8+ T cells in the abscopal tumour was also significantly higher." (PMID 34281259, 2021).
tumor (continued). "Tumor cells and the components of TME, including CD8+ T cells, CD4+ T cells, NK cells, dendritic cells, B cells, macrophages, FOXP3, and Collagen I have close correlations to tumor treatment and prognosis." (PMID 34239944, 2021). "Although an increase in CD4+ T cell population was found in the spleen, no similar increase was found in the tumor." (PMID 34381456, 2021). "Although BCG produces an anti-tumor environment affecting the innate immune system, it has been reported that BCG instillations in NMIBC patients also induce immune anti-tumor responses mediated by CD4+ T cells and CD8+ cytotoxic T lymphocytes." (PMID 33802203, 2021). "We stained CD4 and CD8 for each tumor sample from the discovery cohort and analyzed the percentage of IHC positive cells of the whole tumor, the MPC region that was within the whole tumor, and the peritumor region that surrounded the whole tumor." (PMID 34221970, 2021). "When this tumor border region was interrogated by image cytometry, we identified a statistically significant increase of T-cells—and more specifically of CD4 T-cells—as a fraction of all immune cells (CD45+, Fig. 4gii-v, CD3 p = 0.046, CD4 p = 0.014)." (PMID 34732713, 2021). "Moreover, the treatment of PBMCs from MM patients with RV upregulated CD69 expression on NK cells, CD4+ T cells, CD8+ T and NK showed enhanced degranulation against autologous tumor cells." (PMID 33668361, 2021). "Co-culture of GPC3+ tumor cells, MSCsGPC3-CD3 and T lymphocytes led to the increased production of IFN-γ in GPC3-specific CD4+T cells and the enhanced activation and expansion of GPC3-specific CTLs, which resulted in the efficient CTL-dependent killing of GPC3-expressing malignant cells." (PMID 34830312, 2021). "Tumour infiltrating CD8+ T cells expressed high levels of PD-1 and CD4+ T cells expressed FoxP3 and CTLA4, suggested that immune suppression in the tumour microenvironment may be responsible for downregulation of cytotoxic T cell activity in the tumour." (PMID 34359633, 2021). "The potential impact of targeting PSGL-1 on tumor control is evident from mouse studies, however the question still remains as to whether PSGL-1 blockade affects CD4+ and CD8+ T cells and other immune cells within the TME of human cancers." (PMID 33708224, 2021). "Given that cDC2 is involved in CD4+ T cell differentiation and activation, CD300a on cDC2, rather than cDC1, may regulate Treg cells activation by inhibiting the TLR3–IFN-β pathway in tumor microenvironment." (PMID 34751648, 2021). "pB7S1R was detected on CD4+ T, CD8+ T, natural killer (NK), and NK T cells in tumor tissues." (PMID 34307455, 2021). "Treatment responsive HCCs, however, responded via different immune pathways, with no significant changes observed in CD8+ or myeloid cell populations but instead a significant increase in tumour infiltrating GZB+ NK+ cells and a concomitant decrease in CD4+ T-regulatory cells." (PMID 35936114, 2021). "Although not as extensively studied as for CD8+ T cells, CD4+ T cells within the tumour environment do express markers of exhaustion." (PMID 33597595, 2021). "Either CD4+ Th1 or Th17 cells promote CD8+ cells activation, and a lower infiltration of IL-17A-expressing cells could indicate a diminished anti-tumor response." (PMID 34944746, 2021). "CBP-12-OVA significantly increased the proportion of tumor-infiltrating CD4+ T cells but not NK cells." (PMID 34158852, 2021). "We found that the NLR value in peripheral blood was correlated with the status of CD8-positive TILs in the TME, but not with the expression of PD-L1 in tumour cells and immune cells expressing other markers including CD4, and CD20." (PMID 33250511, 2021). "IFN-γ also stimulates an anti-tumor environment by increasing expression of classical MHC class I genes, cytotoxicity, effector functions, CD4+ and CD8+ T cell proliferation, and survival, while also decreasing Treg suppressive activity and endothelial cell proliferation." (PMID 33669271, 2021).
tumor (continued). "To validate our hypothesis that the tumor-suppressive effect of WSX1 relies on its impact on CD8+ T-cells, we next performed in vivo depletion of CD8+ and CD4+ T-cells as well as NK cells using specific antibodies." (PMID 34108491, 2021). "CD4+CD25++Tregs in the tumour-draining regional lymph node inhibit the proliferation of effector T cells, and Tregs prevent effector T cells from killing tumour cells in the primary tumour tissue." (PMID 33995362, 2021). "When segregating cells this way, 11.3% of all TILs co-expressed LAIR2 and CD4, while only 2.4% of TILs co-expressed LAIR2 and CD8A at log2(TPM + 1) > 4, indicating differences in LAIR2+ expression between different T cell compartments of the tumor samples." (PMID 35008369, 2021). "In case of tumor cell surface membrane aberrant expression of TSA or TAA, MHC class I, and NK cells activating molecules, immunotherapeutic approaches that manipulate number and activity of antibody, CD4+, CD8+, NK cells and macrophages are of limited effect." (PMID 34717628, 2021). "Overall, as only TILs with high level of recognition were used, the mean percentage of “bulk” TILs that were reactive to autologous tumor cells was high (measured with upregulation of CD137, TNF, IFNγ or CD107a: 41% in CD8+ TILs, n=21; and 29% in CD4+ TILs, n=16." (PMID 34707600, 2021). "In naive/Tcm CD4 T cells, there was reduced expression of CD28, ICOS, and OX40 in tumor compared with normal, with little PD1 expression and reduced CTLA4 expression in tumor T cells." (PMID 34936871, 2021). "Of note, the reduction of the quantity of CD4+ and CD8+ CD19.CAR-T cells by NSAIDs might contribute to this inhibitory effect on the anti-tumor activity of CAR-T cells." (PMID 34122428, 2021). "Professional antigen-presenting cells (APCs), like dendritic cells (DCs), can display exogenous tumor antigens on major histocompatibility complex class I (MHC I) or II molecules, priming CD8+ T cells (cytotoxic T lymphocytes, CTLs) or CD4+ T cells (T helper cells, Th), respectively." (PMID 34485282, 2021). "Notably, co-delivery of celecoxib and anti-PD-1 monoclonal antibodies increased the numbers of INF-γ-expressing CD4+ and CD8+ T cells and decreased the numbers of intratumoral Tregs, MDSCs, and PD-L1-positive tumor cells." (PMID 35111169, 2021). "Some studies have reported that TNFAIP expression is upregulated in the infiltrating CD4+/CD8+ T cells of patients with HNC, suggesting that TNFAIPs may be involved in the modulation of tumour progression and immunotherapeutic effects." (PMID 34344926, 2021). "To demonstrate that PLP induced antitumor immunity, we assessed whether IFN-γ-expressing CD4+ and CD8+ T cells in tumor-bearing mice increased due to administration of PLP on day 21 after tumor inoculation." (PMID 34504423, 2021). "The seventh group of recipient BALB/c mice was transplanted with 10 × 106 1bone marrow cells, and recipient mice were also given 2.5 × 106 CD4+ and 2.5 × 106 CD8+ T cells from Itk–/− mice and challenged with 2 × 105 luciferase‐expressing B‐ALL tumour cells (group 7)." (PMID 34919342, 2021). "Consistent with increased tumor-infiltrating lymphocytes (TILs) in tumors, CA170 plus KVax treatment also increased the expression of IFN-γ, TNFα, and granzyme B in tumor-infiltrating CD4+ and CD8+ T cells in tumors." (PMID 34302042, 2021). "Therefore, Treg cells can hamper cancer treatment by infiltrating tumors and hindering antitumor immune responses of tumor antigen-specified CD8+ T cells and CD4+ T cells." (PMID 34055618, 2021). "High response rate to αPD-1/PD-L1 therapy is often associated with immune inflamed cancer phenotype characterized by the presence in the TME of both CD4+ and CD8+ T cells, PD-L1 expression on infiltrating immune and tumor cells and many pro-inflammatory and effector cytokines, such as IFN-γ15." (PMID 33510147, 2021).
tumor (continued). "Researchers demonstrated that KRAS mutations, common in CMS3 CRC subtype, promote an immunosuppressive TME, inducing the conversion of CD4+ cells to Tregs [26, 27•] and, by upregulation of CXCL3 expression, the main ligand of CXCR2 on MDSCs surface, support their migration inside tumor core." (PMID 34110510, 2021). "Studies have shown that CD4+ T cells may activate STAT3 through CCL5 to affect the chemosensitivity of PCa, and the expression of MHC I increases the immunogenicity of PCa tumor cells." (PMID 34215720, 2021). "Further analysis of the DN population based on CD25 and CD44 expression revealed that in tumor-free thymi, most ALK+ cells were DN3 (CD25+CD44−) and DN4 (CD25−CD44−) stage thymocytes, which correlates with the developmental stages at which Cd4 driven NPM-ALK expression was induced." (PMID 33310759, 2021). "Downregulation of COX-2 results in a decrease in CD4+CD25+ Tregs and tumor regression." (PMID 33628741, 2021). "In vitro, PD-1 blockade enhanced CD4 TIL activation, as evidenced by increased CD154 expression and cytokine secretion, leading to improved dendritic cell maturation and consequently higher tumor-specific CD8 T cell proliferation." (PMID 33332284, 2021). "Future studies are need to determine if other alterations in CD8 or CD4 extracellular domains could be used to further stabilize the TCR’s interaction with low affinity tumor antigens and thereby improve anti-tumor CD8 and CD4 effects respectively." (PMID 34012443, 2021). "In terms of the T cell and B cell composition within lymph nodes, CD4+ T cells, CD8+ T cells, and B cells were significantly increased in the mice immunized with tEV plus SyBV, implying the induction of tumour‐specific adaptive immunity by SyBV." (PMID 34262675, 2021). "The study will include analyses of CD45+CD4+CD25+FoxP3+T cells and CD25+FoxP3+T cells in the peripheral blood, as well as the distribution of CD8+ and Foxp3+ (immunoreactive/suppressor) T cells in different regions of tumor lesions." (PMID 34302324, 2021). "This suggests there is a pressing need to explore other cytokines that can successfully expand tumor specific CD4+ T cells without generating regulatory T cells." (PMID 34012451, 2021). "In immunocompetent mice implanted with subcutaneous Lewis lung cancer cells, GSK126 (EZH2i) treatment led to accumulation of myeloid-derived suppressor cells (MDSC) and decreased numbers of CD4+ T cells and CD8+ T cells, which masked the anti-tumour effects of EZH2i." (PMID 34439236, 2021). "The large expansion of tumor-specific Tc was critical for durable tumor regression, as depletion of Tc (by αCD8), but not CD4 T helper cells (Th; by αCD4), diminished the efficacy of RT in tumor-bearing Sirpα−/− mice." (PMID 34050181, 2021). "Frequency of CD8+, CD4+ T cells and other cytokines in MFC spleen and tumor tissue." (PMID 33981600, 2021). "Flow cytometric analysis of blood, spleen and the lung TME showed that VNS had no impact on the RT-induced reduction of CD8+ T cells nor on the RT-mediated rise in tumor infiltrated CD4+ T cells." (PMID 34925341, 2021). "Indeed, in co-culture with macrophages and murlentamab-opsonized tumor cells, we reported an increased proportion of activated CD8+ and Th1 CD4+ T cells as well as a reduced proportion of CD25+ CD4+ Tregs." (PMID 33924378, 2021). "Strikingly, we observed a higher CD8+/CD4+ ratio in lexatumumab + ROCK1i and lexatumumab + avelumab‐treated 4T1 tumors but not in DR5 agonist alone treated tumors (n = 6–20 tumor‐bearing animals, three separate experiments)." (PMID 33587338, 2021). "The present study supports the premise that the tumor inhibitory effects of EP54 are due to immunoregulatory mechanisms, with EP54-treated mice showing increased tumor infiltration by T lymphocytes, in particular CD4+ T cell subsets, Th1 and Th17." (PMID 33430104, 2021).